MIR4451 (microRNA 4451)
Synonyms: hsa-mir-4451; mir-4451
Gene: MicroRNA gene on chromosome 4 (85,722,468 to 85,722,533, forward strand). Ensembl gene ENSG00000266421.
Homologues: Orthologues: chimpanzee MIR4451 (100% identical).